RYR2 (ryanodine receptor 2)
Diseases named in the same sentence as RYR2 in open-access papers (continued):
Sharing a sentence is not in itself a finding about the gene and the disease.
cardiac diseases (61 papers, 2009 to 2026). "By integrating recent high-resolution cryo-EM structural analyses with molecular and cellular studies on RyR2 regulation, as well as clinical evidence of RyR2 mutations in arrhythmogenic heart diseases, we provide a comprehensive overview of the field." (PMID 41898308, 2026). "One common host gene association emerged from all the cardiac disease and cardiac muscle contraction pathways: Ryanodine receptor 2 (Ryr2)." (PMID 37047531, 2023). "Numerous mutations in the gene encoding RyR2 protein have been identified and many are linked to a wide spectrum of arrhythmic heart disease." (PMID 35892340, 2022). "The proband’s DNA was screened using a genetic testing panel for cardiac diseases and the only variant found as potentially pathogenic was D3291V in RYR2 at the heterozygous state." (PMID 34202968, 2021). "Although RYR2 is known to be associated with heart disease, RYR2 as one of the components of a calcium channel that also influences calcium signaling in airway smooth muscle cells." (PMID 31480292, 2019). "Posttranslational modifications of the channel, including phosphorylation by PKA and/or CaMKII and oxidation of reactive cysteines, have been implicated in the RyR2 hyperactivity characteristic of cardiac disease and aging." (PMID 31636573, 2019). "Primarily located in T-tubules in junctional SR, LTCCs form clusters that oppose clusters of RyR2 channels, and changes in T-tubule structure and function have been implicated in impaired contractility observed in cardiac disease." (PMID 31091723, 2019). "Stabilization of RyR2-mediated Ca release can be achieved indirectly by targeting CaMKII, given chronic activity in cardiac disease has been linked to RyR2 channel dysfunction." (PMID 30425651, 2018). "RyR3 protein mobilizes stored Ca + 2 in both cardiac and skeletal muscle to initiate muscle contraction and dysregulation of both RyR2 and RyR3 that have been associated with cardiac diseases." (PMID 25750702, 2015). "Similar to SCN5A, mutations in ryanodine receptors (RyR2) have been reported in cardiac diseases." (PMID 41510139, 2026). "Cardiac disease is associated with deleterious emission of mitochondrial reactive oxygen species (mito-ROS), as well as enhanced oxidation and activity of the sarcoplasmic reticulum (SR) Ca2+ release channel, the ryanodine receptor (RyR2)." (PMID 32444920, 2020). "The altered phosphorylation status of RyR2 and changes in the activity of associated kinases and phosphatases have long been implicated in aberrant Ca2+ cycling, and this has been well documented in many animal models of cardiac disease, as well as in humans." (PMID 31091723, 2019). "All these results suggested that the acute PM2.5 exposure might increase the risk of heart diseases and even death by altering calcium homeostasis through RYR2 and SERCA2a in this model." (PMID 30837634, 2019). "Understanding these interactions could be important as such anomalies may be associated with the increased RyR2-mediated Ca2+ leak observed in cardiac diseases." (PMID 20016815, 2009). "However, the effects of numerous RyR2 mutations remain unclear, and deeper mechanistic insights will lay a key foundation for developing novel therapies against RyR2-related cardiac diseases." (PMID 41898308, 2026). "Several wrongly classified genes were associated with inherited cardiac diseases, such as SCN5A, KCNQ1, and RYR2, which renders the tissues less suitable for reliable gene expression examinations in relation to cardiac disease." (PMID 40373069, 2025). "For instance suppressing CaMKII activity reduced dispersion of activation in engineered human CPVT heart tissue, and inhibiting RyR2 with dantrolene reduced dispersion of repolarization in a guinea pig model of non-ischaemic heart disease." (PMID 40612651, 2025).
cardiac diseases (continued). "This study uses previously developed RyR biosensors to screen a 50K-compound library for drug-like small molecules that target RyR2 dysfunction, as early-stage screening for therapeutics for heart disease and neurodegeneration." (PMID 41260336, 2025). "This review examines RYR2 dysfunction in terms of channel structure and function modulation and explores potential therapeutic approaches to stabilize RYR2 function in heart disease." (PMID 40910028, 2025). "In the context of heart disease, p-CaMKII plays a critical regulatory role in calcium handling by modulating key proteins such as RyR2 and PLB." (PMID 40650101, 2025). "Vice versa, small chemical molecules that directly enhance the association of FKBP12.6 to RyR2, namely JTV-519 (K201) and S107, improved cardiac muscle function in experimental models of heart disease." (PMID 38012000, 2024). "Cardiac ryanodine receptor (RyR2), the Ca2+ release channel of the sarcoplasmic reticulum, is believed to be a good therapeutic target in a group of certain heart diseases, collectively called cardiac ryanopathies." (PMID 35457253, 2022). "For example, the PKA phosphorylation of PLB are usually suppressed in heart failure, whereas the PKA phosphorylation of RyR2 is often elevated in cardiac diseases." (PMID 36104752, 2022). "Further study will help understand how the cardiac β1AR is uncoupled from the RyR2 nanodomains during the development of cardiac diseases." (PMID 36104752, 2022). "A novel classification for genetic RyR2-related cardiac disease was recently proposed as a typical and atypical CPVT." (PMID 35892340, 2022). "Abnormal RyR2 gating perturbs cardiomyocyte Ca2+ handling resulting in acquired and inherited arrhythmogenic cardiac disease." (PMID 32077934, 2021). "Post-translational modification of RyR2 channels is involved in several forms of heart disease and contributes to abnormal intracellular calcium handling." (PMID 34497331, 2021). "This is, to the best of our knowledge, the first study to examine RyR2 clustering properties in human cardiac disease using dSTORM." (PMID 33718369, 2021). "Further studies are needed to define the specific molecular steps that mediate reduced RyR2 CaMKII phosphorylation by PYR in different cardiac disease settings." (PMID 33755308, 2021). "Aging alone results in advanced glycation of RyR2, leading to increased SR Ca2+ leak, mitochondrial Ca2+ overload and mitochondrial dysfunction, independently of cardiac disease." (PMID 33013458, 2020). "Diastolic Ca2+ release via leaky RyR2 is a key mechanism for contractile dysfunction and arrhythmias in HF and other cardiac diseases." (PMID 33034709, 2020). "In cardiac disease or aging, RyR2 becomes more active, which likely helps maintain cardiac output to meet baseline metabolic demands." (PMID 31636573, 2019). "Targeting of mitochondrial ROS and, thus, hyperactive RyR2, therefore, remains an attractive therapeutic target for arrhythmogenesis in cardiac disease and aging." (PMID 31091723, 2019). "Herein we review the most recent insights into redox-dependent modulation of RyR2 during oxidative stress and heart diseases." (PMID 30574097, 2018). "It is also well established that chronic CaMKII activity in cardiac disease is a major regulator of RyR2 function with arrhythmogenic consequences." (PMID 30425651, 2018). "Furthermore, reactive oxygen species (ROS) can induce RyR2 oxidation, establishing a pathological Ca2+ leak-ROS cycle in heart disease." (PMID 41898308, 2026). "Changes in RYR2 protein levels have also been noted in the pathogenesis of cardiac diseases." (PMID 39041002, 2024). "In addition, several proteins identified have links to heart disease and were identified having a role in rodent models of RyR2 haploinsufficiency." (PMID 39041002, 2024).
cardiac diseases (continued). "In contrast to RyR1, the cardiac-disease associated RyR2 mutation, located in the domain interface between the EF hand and S2–S3 loop, did not exhibit a large impact on Ca2+ inhibition of RyR2." (PMID 38159862, 2023). "The cardiac ryanodine receptor (RyR2), which mediates intracellular Ca2+ release to trigger cardiomyocyte contraction, participates in development of acquired and inherited arrhythmogenic cardiac disease." (PMID 32077934, 2021). "However, as β-adrenergic drive can exacerbate Ca2+ leak from RyR2 channels that are already hyperactive in cardiac disease, the detrimental effects of excessive diastolic Ca2+ leak are most obvious during this response." (PMID 32444920, 2020). "Ryanodine receptor 2 (RyR2) and SERCA2a are two major players in myocyte calcium (Ca) cycling that are modulated physiologically, affected by disease and thus considered to be potential targets for cardiac disease therapy." (PMID 32260593, 2020). "Our results suggest that increased RyR2 activity disturbs mito-Ca2+ homeostasis and elevates mito-ROS emission, thus in a vicious feedback cycle exacerbates diastolic SR Ca2+ leak by increasing RyR2 oxidation, driving spontaneous Ca2+ release that is detrimental in cardiac disease." (PMID 32444920, 2020). "In addition, RyR2 mutations have also been implicated in non-stress-induced cardiac disease including long QT syndrome, torsade de pointes, left ventricular noncompaction, dilated cardiomyopathy, and hypertrophic cardiomyopathy." (PMID 35892340, 2022). "In most cases, both the RyR2-mutated patients and RyR2-mutated mice show non-organic heart disease." (PMID 31143551, 2019). "While RyR2 function resulting from targeted single post-translational modification (e.g., the effects of single phosphorylation at specific sites) has been largely studied in channels re-expressed in bilayers, the complex RyR2 alterations that occur in cardiac diseases cannot be reproduced in vitro." (PMID 30410446, 2018). "Additionally, oxidation as a posttranslational modification may alter RyR2 function in cardiac disease." (PMID 30425651, 2018). "In summary, our findings introduce a novel RyR2 structure-function parameter, namely, the NTD-CSol inter-subunit interaction, in the pathogenesis of arrhythmogenic cardiac disease." (PMID 39777228, 2024). "While the ryanodine receptor (RYR2) has been related to cardiac diseases, research on bleeding complications is lacking." (PMID 38034995, 2023). "In this first study to examine nanoscale RyR2 organization in human cardiac disease, these findings indicate that RyR2 cluster remodeling is not an underlying mechanism contributing to altered channel function and subsequent arrhythmogenesis in human AF." (PMID 33718369, 2021). "However, the functional role of PKA-mediated RyR2 phosphorylation remains controversial and many studies have shown phosphorylation at the S2808 site does not modulate channel activity in other cardiac disease states." (PMID 30425651, 2018).
cancer (54 papers, 2011 to 2025). A tumor composed of atypical neoplastic, often pleomorphic cells that invade other tissues. "Advancements in high‐throughput sequencing technology have revealed that RYR2 is one of the most frequently mutated genes in various cancers." (PMID 40200715, 2025). "Researches have demonstrated that dysregulation of RYR2 is associated with development and progression of various cancers." (PMID 39658878, 2024). "Collectively, these studies present evidence that RYR2 mutation predicts a positive response to immunotherapy in multiple human cancers." (PMID 37079639, 2023). "Recently, RYR2 was found to be one of the most mutated genes in multiple kinds of cancers." (PMID 40200715, 2025). "RYR2 mutations affect Ca2+ signaling pathways, which are crucial for cell proliferation and metastasis, the most important factors in the pathogenesis of various cancers." (PMID 39408657, 2024). "There is a high frequency of RYR2 mutations in various types of cancer in humans." (PMID 36588677, 2022). "Mutations in RYR2 gene are known to occur during transformation of oral dysplasia to cancer." (PMID 34136393, 2021). "Importantly, only RYR2 was reported for the first time as the mutated cancer driver according to the Cancer Gene Census and IntOGen." (PMID 31480292, 2019). "There is strong evidence that ryanodine receptor 2 (RYR2) plays an important role in different types of cancer according to previous studies." (PMID 39408657, 2024). "More specifically, somatic mutations and RYR2 promoter methylation contribute to the pathogenesis of HNSCC by disrupting normal cellular functions and promoting cancer progression." (PMID 39408657, 2024). "Similar results were also obtained for other cancer genes such as RYR2, indicating biases in the frequencies between mutations that did or did not cause nullomer emergence across patients." (PMID 38351138, 2024). "And dysregulation of ryanodine receptor 2 (RyR2) is also related to cancer development and progression in TNBC." (PMID 39658878, 2024). "S107, an approved drug to inhibit calcium release from RyR2 in the clinic, inhibited cancer cell metastasis both in vitro and in vivo." (PMID 36453019, 2023). "The mutational landscape of our LUAD cohort was very similar to what is expected for this cancer type, with KRAS being the top mutated gene (41%) followed by RYR2 (34%) and MUC16 (32%)." (PMID 37501683, 2023). "RyR2 gene silencing by knocking down or pharmacological inhibition by small molecule S107 decreased cancer cell metastasis both in vitro and in vivo." (PMID 36453019, 2023). "Previous studies on RyR2 were mainly focused on the physiological and pathological roles in heart and brain, where RyR2 was highly expressed; few studies have reported its role in cancer metastasis." (PMID 36453019, 2023). "The ability of S107 to inhibit cancer cell metastasis and ROS production was consistent with the results of RyR2 KD." (PMID 36453019, 2023). "Although the number of mutations in RYR2 was significantly higher than RYR1 and RYR3, the ratio of mutation categories in most cancer types was relatively consistent." (PMID 36167878, 2022). "In order to understand the distinct mutational status of each cancer type, we further analyzed the ratio of RYR1, RYR2 and RYR3 mutation types in 30 different cancers." (PMID 36167878, 2022). "Real-time PCR results confirmed that the RyR isoform 2 (RyR2) was mainly expressed in HeLa cancer cells." (PMID 31882989, 2019).
cancer (continued). "Other cancer genes frequently altered in LC according to cBioPortal (e.g., ZFHX4, RYR2, CSMD3, FAT3, and RP1L1) were also found mutated at a high frequency in our cohort." (PMID 30925779, 2019). "We additionally identified recurrent mutations in RYR2, FMN1, B3GNT9 and PIEZO2 in our discovery set of cancers, but the importance of these genes for bladder carcinogenesis remains uncertain." (PMID 24777035, 2014). "Other genes, such as RYR2 and ANO1, both related to KRAS Signaling in the MSigDB “Hallmark Gene Sets”, were proposed for the hallmark of “Sustaining Proliferative Signaling”, underscoring their role in uncontrolled cell proliferation, a hallmark of cancer." (PMID 40136626, 2025). "Moreover, these two SBS subtypes differed in somatic mutations in several cancer driver genes, including higher mutation frequency of ERBB2, GATA3 and FGFR4, and lower frequency of DMD, INHBA, OGDHL, PLEKHG5 and RYR2 in subtype 3 than in subtype 1 (P < 0.05)." (PMID 40858906, 2025). "The main pathways of methylome biomarkers were associated with calcium signalling (CACNA1E, RYR2, RYR3), cancer pathways (DCC, RASSF1, WNT1, CTNNA2), multiple neurodegenerative diseases (WNT1, DNAI1, RYR2, RYR3), immune system disorders and cell adhesion (HLA-DRA, HLA-DRB1, HLA-DRB5)." (PMID 40524349, 2025). "However, research on the role of RYR2 in cancer is still in its early stages, and some findings are contradictory." (PMID 40200715, 2025). "The Ryr2 mRNA expression was also increased in the anti-PD-L1-treated GCV mice compared to isotype Ctrl GCV mice suggesting that anti-PD-L1 per se increases cardiac expression indepently of cancer disease." (PMID 39834851, 2024). "Additionally, higher RYR2 levels were also detected in patients with T4 cancer than those with T2 and T3 cancer (p = 0.0349 and 0.0092, respectively)." (PMID 39408657, 2024). "Current DNA methylation-based biomarker studies focus on the influence of promoter hypermethylation in tumor suppressor genes (such as RYR2), which may alter cancer signaling transduction and promote the formation and development of cancer." (PMID 32724310, 2020). "In addition, neferine-mediated GFP-LC3 puncta formation and cell death were markedly diminished in HeLa cancer cells silenced with RyR2 siRNA." (PMID 31882989, 2019). "Only two signatures (MUC12 and RYR2) predicted prognosis in ER-negative/HER2-negative cancers." (PMID 29559730, 2018). "We previously noted that RYR2 could be related to the occurrence and prognosis of various cancers." (PMID 39408657, 2024). "Therefore, exploring the relationship between RYR2 SNPs and the development of OSCC in Taiwanese individuals could provide valuable information on the genetic mechanisms underlying this cancer." (PMID 39408657, 2024). "Finally, it remains important to assess whether gain of function for RyR2 in Tregs contributes to aberrant inflammation or autoimmunity or could be used therapeutically for the treatment of cancer." (PMID 38099491, 2023). "Furthermore, RYR2 is an important player in steroid metabolism and cancer research." (PMID 35975176, 2022). "Here, we identified that ryanodine receptor 2 (RyR2) expression was upregulated in KRAS‐mutant mCRC, and that this promoted cancer cell metastasis." (PMID 36453019, 2023). "The methylation profile of ryanodine receptor 2 (RYR2) and the resulting mRNA expression motif are highly unstable in both cancer-derived samples and HNSCC cell lines." (PMID 36769317, 2023). "Co-occurrence of genetic mutations in tumors with PARP1 alterations involved some genes that were enriched in transcriptional misregulation in cancer pathways (e.g., H3F3A, HIST3H3) and calcium signaling pathways (e.g., ITPKB, RYR2)." (PMID 34531868, 2021). "The results of interactive network analysis provide new perspectives on the role of hub genes, along with RYR2, ERBB2, PIK3CA, and HELZ2, with respect to the development of GC by querying multidimensional cancer genomics data in cBioPortal." (PMID 32801999, 2020).